LPCAT3 (lysophosphatidylcholine acyltransferase 3)
Description:
Lysophospholipid O-acyltransferase (LPLAT) that catalyzes the reacylation step of the phospholipid remodeling process also known as the Lands cycle. Catalyzes transfer of the fatty acyl chain from fatty acyl-CoA to 1-acyl lysophospholipid to form various classes of phospholipids. Converts 1-acyl lysophosphatidylcholine (LPC) into phosphatidylcholine (PC) (LPCAT activity), 1-acyl lysophosphatidylserine (LPS) into phosphatidylserine (PS) (LPSAT activity) and 1-acyl lysophosphatidylethanolamine (LPE) into phosphatidylethanolamine (PE) (LPEAT activity). Favors polyunsaturated fatty acyl-CoAs as acyl donors compared to saturated fatty acyl-CoAs. Has higher activity for LPC acyl acceptors compared to LPEs and LPSs. Can also transfer the fatty acyl chain from fatty acyl-CoA to 1-O-alkyl lysophospholipid or 1-O-alkenyl lysophospholipid with lower efficiency (By similarity). Acts as a major LPC O-acyltransferase in liver and intestine. As a component of the liver X receptor/NR1H3 or NR1H2 signaling pathway, mainly catalyzes the incorporation of arachidonate into PCs of endoplasmic reticulum (ER) membranes, increasing membrane dynamics and enabling triacylglycerols transfer to nascent very low-density lipoprotein (VLDL) particles. Promotes processing of sterol regulatory protein SREBF1 in hepatocytes, likely by facilitating the translocation of SREBF1-SCAP complex from ER to the Golgi apparatus (By similarity). Participates in mechanisms by which the liver X receptor/NR1H3 or NR1H2 signaling pathway counteracts lipid-induced ER stress response and inflammation. Down-regulates hepatic inflammation by limiting arachidonic acid availability for synthesis of inflammatory eicosanoids, such as prostaglandins (By similarity). In enterocytes, acts as a component of a gut-brain feedback loop that coordinates dietary lipid absorption and food intake. Regulates the abundance of PCs containing linoleate and arachidonate in enterocyte membranes, enabling passive diffusion of fatty acids and cholesterol across the membrane for efficient chylomicron assembly (By similarity). In the intestinal crypt, acts as a component of dietary-responsive phospholipid-cholesterol axis, regulating the biosynthesis of cholesterol and its mitogenic effects on intestinal stem cells (By similarity).
Synonyms: LPLAT 5; LPCAT; LPSAT; MBOAT5; OACT5; C3F; nessy; LPLAT12
Tractability: Antibody: UniProt predicts a signal peptide or a membrane-spanning region. PROTAC: ubiquitination databases record sites on it; its protein half-life has been measured.
Target class: Enzyme; Transferase
Gene: Protein-coding gene on chromosome 12 (6,976,176 to 7,018,538, reverse strand). Ensembl gene ENSG00000111684.
Subcellular location: Endoplasmic reticulum membrane
Pathways (Reactome):
Metabolism: Acyl chain remodelling of PC; Acyl chain remodelling of PE; Acyl chain remodelling of PS
Gene Ontology:
Molecular function: 1-acylglycerophosphocholine O-acyltransferase activity; 1-acylglycerophosphoethanolamine O-acyltransferase activity; 1-acylglycerophosphoserine O-acyltransferase activity; 1-acylglycerol-3-phosphate O-acyltransferase activity; 2-acylglycerol-3-phosphate O-acyltransferase activity; lysophospholipid acyltransferase activity; 1-alkenylglycerophosphoethanolamine O-acyltransferase activity
Biological process: phosphatidylcholine acyl-chain remodeling; phosphatidylethanolamine acyl-chain remodeling; phosphatidylserine acyl-chain remodeling; chylomicron assembly; endoplasmic reticulum membrane organization; intestinal stem cell homeostasis; lipid modification; negative regulation of inflammatory response; negative regulation of response to endoplasmic reticulum stress; phosphatidylcholine biosynthetic process; positive regulation of intestinal cholesterol absorption; positive regulation of triglyceride transport; regulation of cholesterol biosynthetic process; very-low-density lipoprotein particle assembly; phospholipid metabolic process
Cellular component: endoplasmic reticulum membrane; membrane
Genetic constraint (gnomAD): Loss-of-function variants: 17 observed, 52.56 expected, observed/expected ratio (o/e) 0.32, 90% interval 0.22 to 0.49. The upper end of that interval is the gene's LOEUF score, 0.49, which puts it in group 2 of 6, group 1 being the genes least tolerant of losing a copy. Missense variants: 410 observed, 544.83 expected, observed/expected ratio (o/e) 0.75, 90% interval 0.69 to 0.82. Synonymous variants: 213 observed, 212.63 expected, observed/expected ratio (o/e) 1, 90% interval 0.89 to 1.12.
Homologues: Orthologues: chimpanzee LPCAT3 (99% identical), macaque LPCAT3 (98% identical), dog LPCAT3 (92% identical), pig LPCAT3 (90% identical), rabbit LPCAT3 (89% identical), mouse Lpcat3 (87% identical), guinea pig LPCAT3 (87% identical), rat Lpcat3 (87% identical), zebrafish lpcat3 (61% identical), Drosophila melanogaster nes (36% identical), Caenorhabditis elegans mboa-6 (32% identical). Paralogues in human: MBOAT1 (22% identical), MBOAT2 (21% identical), MBOAT7 (20% identical), PORCN (17% identical), MBOAT4 (16% identical).
Diseases named in the same sentence as LPCAT3 in open-access papers:
LPCAT3 is named in the same sentence as 73 diseases in open-access papers, as found by Europe PMC text mining. Sharing a sentence is not in itself a finding about the gene and the disease. The quoted sentences say what the papers report.
atherosclerosis (13 papers, 2018 to 2025). A disease characterized by the build-up of fatty material and calcium deposition in the arterial wall resulting in partial or complete occlusion of the arterial lumen. "LPCAT3 is a major regulator of free AA levels, which are a key factor associated with the development of atherosclerosis 38,39." (PMID 35711841, 2022). "An article clearly indicates that the development of atherosclerosis is closely associated with high expression of Lpcat3." (PMID 35122680, 2022). "Next, we wanted to address the impact of Lpcat3 deficiency on macrophage lipid homeostasis and atherosclerosis development." (PMID 33518513, 2021). "Recent biological evidence suggests strong causal links between PCOLCE2 activity and atherosclerosis, while a series of recent articles are beginning to tease out the phospholipid related functionality of LPCAT3." (PMID 29652918, 2018). "In this study, we utilized myeloid cell-specific Lpcat3 deficient mice to study the effect of Lpcat3 deficiency on cholesterol efflux, inflammation, and atherosclerosis." (PMID 30705887, 2018). "Very recently, it has been reported that Lpcat3 deficiency in hematopoietic cells influence cholesterol and phospholipid metabolism and promotes atherosclerosis in a mouse model." (PMID 30705887, 2018). "This would seem to suggest that macrophage LPCAT3 deficiency may exacerbate atherosclerosis by promoting an inflammatory response." (PMID 35711841, 2022). "Moreover, we investigated the impact of macrophage Lpcat3 deficiency in mouse models of atherosclerosis and obesity/hepatic steatosis." (PMID 33518513, 2021). "However, these mice presented a total Lpcat3 deficiency in all the hematopoietic lineages, including hematopoietic stem cells, which is likely to contribute to atherosclerosis development." (PMID 33518513, 2021). "On the one hand, the expression of LPCAT3 is associated with atherosclerosis progression." (PMID 34824256, 2021). "Finally, we found that myeloid cell-specific Lpcat3-deficiency had no significant changes in atherogenesis, while, hematopoietic-specific Lpcat3-deficiency promotes atherosclerosis." (PMID 30705887, 2018). "Moreover, the presence of fatty liver disease and atherosclerosis, which are associated with complex metabolic and inflammatory alterations, might indirectly impact LPCAT3 levels." (PMID 40737292, 2025). "On the other hand, although LPCAT3 deficiency in macrophage increases the production of inflammatory and atherogenic cytokines/chemokines, however, this effect may29 or may not30 promote the development of atherosclerosis." (PMID 34824256, 2021). "In the context of atherosclerosis, LPCAT3 is essential for regulating phospholipid metabolism, cholesterol homeostasis, cholesterol efflux, and inflammatory responses." (PMID 40737292, 2025). "Together, these findings highlight the therapeutic potential of targeting the LPCAT3-ELOVL5 axis for nutritional or pharmacological interventions in atherosclerosis." (PMID 40345182, 2025). "We show in an atherosclerosis mouse model that a combined Lpcat3/Elovl5 deletion in macrophages results in higher necrotic core area, a phenomenon linked to heightened macrophage sensitivity to cytotoxic oxysterols such as 7-ketocholesterol (7-KC)." (PMID 40345182, 2025).
atherosclerosis (continued). "Over the past decade, studies have highlighted the role of LPCAT3 in some diseases, such as atherosclerosis." (PMID 38694208, 2024). "Increasing lines of research have demonstrated that LPCAT3 plays important roles in the occurrence and development of many diseases, such as atherosclerosis, intestinal tumors, and nonalcoholic steatohepatitis (NASH)." (PMID 35711841, 2022). "Our aim was to investigate the function of LPCAT3 in macrophages in vitro but also in vivo in experimental models of atherosclerosis and obesity." (PMID 33518513, 2021). "Here, we investigated LPCAT3's role in macrophages both in vitro and in vivo in mice with atherosclerosis and obesity." (PMID 33518513, 2021). "Multiple lines of evidence suggest that LPCAT3 is involved in several diseases, including atherosclerosis, non‐alcoholic steatohepatitis, and carcinoma." (PMID 31376210, 2019). "Growing evidence suggests that LPCAT3 is critically involved in the development of several pathologies that include skeletal muscle myopathy, atherosclerosis, acute kidney disease, nonalcoholic steatohepatitis, hyperuricemia, cancer, and other metabolic diseases." (PMID 38519981, 2024). "Increasingly, LPCAT3 has been found to play an important role in the development and progression of diseases such as atherosclerosis, NASH, intestinal tumors, diabetes, and skeletal muscle myopathy and is likely to be a potential therapeutic target for these diseases in the future." (PMID 35711841, 2022). "In addition, there is abundant LPCAT3 expression in vascular smooth muscle cells, which plays an important role in the progression of atherosclerosis." (PMID 35711841, 2022). "Therefore, the modulation of arachidonic acid-PC accumulation and LPCAT3 expression in vascular smooth muscle cells may be a potential means to inhibit the progression of atherosclerosis, which remains to be further demonstrated." (PMID 35711841, 2022). "While Lpcat3 macrophage deficiency did not affect atherosclerosis development, Lpcat3KOMac mice presented with a mild increase in hepatic steatosis under a high-fat diet (HFD) that was associated with alterations of several metabolic pathways and liver eicosanoid composition." (PMID 33518513, 2021). "Importantly, the top genes enriched in LPCAT3+ macrophages are primarily involved in lipid metabolism, phagocytosis, and inflammatory response, indicating that these macrophages are well adapted to environments characterized by lipid accumulation or inflammatory stimuli, as seen in atherosclerosis." (PMID 40345182, 2025). "Regulation of LPCAT3 expression by LXR agonist has also been demonstrated in macrophages and human monocytes and is involved in atherosclerosis development." (PMID 38694208, 2024). "LPCAT3 regulates other inflammatory factors such as LPC and AA, in vascular smooth muscle, thereby exacerbating atherosclerosis." (PMID 38519981, 2024). "In summary, in macrophages, LPCAT3 exerts a proinflammatory effect by regulating the expression of C-SRC and TLR4, thereby promoting the further development of atherosclerosis." (PMID 35711841, 2022). "At the same time, LPCAT3 can also regulate two inflammatory proinflammatory factors, LPC and AA, in vascular smooth muscle, thereby exacerbating atherosclerosis." (PMID 35711841, 2022). "However, macrophage specific Lpcat3 deficiency on atherosclerosis is still not precisely evaluated." (PMID 30705887, 2018). "Hematopoietic cell-specific Lpcat3 knockout in mice exacerbates atherosclerosis, whereas macrophage-specific deletion has no substantial impact on atherogenesis." (PMID 40737292, 2025).
atherosclerosis (continued). "LPCAT3 regulates the expression of C-SRC and TLR4, and promotes the development of atherosclerosis." (PMID 38519981, 2024).
Obesity (10 papers, 2015 to 2025). Accumulation of substantial excess body fat. "Recognizing the importance of understanding the intricate associations among LPCAT3, obesity, and T2DM is paramount." (PMID 40737292, 2025). "Conversely, mice with liver-specific or small intestine-specific LPCAT3 deficiency exhibit reduced subcutaneous white adipose tissue, weight loss, and resistance to obesity." (PMID 40737292, 2025). "Taken together, these results demonstrate that loss of Lpcat3 protects mice from diet‐induced obesity likely through increased energy expenditure." (PMID 37088778, 2023). "LPCAT3 has been implicated in obesity induced skeletal myopathy, with mice overexpressing LPCAT3 exhibiting worse skeletal myopathy when fed a high-fat diet then those mice fed a normal diet." (PMID 37250116, 2023). "The elevation in LysoPCs was therefore consistent with obesity causing a disproportional increase in the rate of both de novo PC synthesis and hydrolysis that exceeded the capacity of LPCAT3 to re-esterify Lyso-PC back into PC." (PMID 31418690, 2019). "LPCAT3 has been implicated in many diseases, particularly insulin resistance in obesity." (PMID 38893234, 2024). "We investigated the impact of macrophage-specific Lpcat3 deficiency on progression of obesity." (PMID 33518513, 2021). "It is plausible that the association between LPCAT3 and T2DM is indirect, potentially mediated by obesity and adipocyte-related biological mechanisms." (PMID 40737292, 2025). "Hepatic phospholipid (PL) saturation, mediated by depletion of a PL remodeling enzyme LPCAT3, protects mice from diet‐induced obesity through FGF21 and elevated energy expenditure." (PMID 37088778, 2023). "Deletion of Lpcat3 ameliorates insulin resistance and blunts lipogenesis in both diet‐ and obesity‐induced models, thus alleviating the deleterious effects of insulin resistance on both glucose and lipid metabolism." (PMID 37088778, 2023). "One attractive additional player is the phospholipid-remodeling enzyme Lpcat3, which we have recently shown affects inflammatory signaling in hepatocytes in the setting of obesity." (PMID 26173179, 2015). "Our prior studies showed that acute shRNA-mediated knockdown of Lpcat3 expression in liver exacerbated ER in the setting of obesity and hepatic steatosis." (PMID 25806685, 2015). "Moreover, the association between LPCAT3 and T2DM risk is likely confounded by obesity-related factors." (PMID 40737292, 2025). "Notably, obesity not only directly affects membrane lipid composition, leading to decreased fluidity, but also modulates LPCAT3 expression in the liver and skeletal muscle, thereby influencing glycerophospholipid remodeling in cell membranes." (PMID 40737292, 2025). "Also, in adipose tissue, LPCAT3 reduces the proinflammatory response of this tissue in obesity, which is related to the reduction of ROS generation by decreasing the activity of NADPH oxidases." (PMID 38893234, 2024). "Overexpression of LPCAT3 in muscle during obesity also leads to myopathy." (PMID 38893234, 2024). "LPCAT3 is consequently a therapeutic target for treatment of obesity induced skeletal myopathy." (PMID 37250116, 2023). "Accordingly, it has been shown that SCD1, LPCAT3, and LCAT activity correlates with membrane saturation, wherein elevated ER stress was observed upon loss of either SCD1 or LPCAT3 activity, and was associated with an increased level of LCAT in animal models of either obesity or overnutrition." (PMID 33277471, 2020). "Subsequent multiple linear regression models and PLS analysis further reveal an unstable yet complex relationship between the three obesity-related anthropometric parameters included in this study (BMI, WC, and WHR) and serum LPCAT3 levels." (PMID 40737292, 2025). "Thus, LPCAT3 may, in some ways, protect the body from some of the effects of obesity." (PMID 38893234, 2024).
Obesity (continued). "While tissue-specific suppression of LPCAT3 expression has been shown to confer resistance to weight gain in preclinical models, our research reveals a potential negative trend between serum LPCAT3 levels and obesity-related anthropometric measures." (PMID 40737292, 2025). "Notably, when serum LPCAT3 is used as a predictor for the onset of T2DM, its predictive power diminishes after adjusting for obesity-related anthropometric measures." (PMID 40737292, 2025). "Our study has uncovered a notable negative correlation between serum LPCAT3 levels and obesity-related body measurements, including BMI and WC." (PMID 40737292, 2025).
Hepatic steatosis (9 papers, 2015 to 2025). Steatosis is a term used to denote lipid accumulation within hepatocytes. "While the molecular mechanisms linking hepatic steatosis and myeloid Lpcat3 deficiency remain to be elucidated, our hypothesis is that changes in AA metabolism-restricted liver myeloid cells may secondarily impact AA homeostasis in the whole liver leading to metabolic disorders and TG accumulation." (PMID 33518513, 2021). "There are several reports that mice lacking PEMT or with reduced LPCAT3 expression exhibit severe fatty liver conditions." (PMID 38953111, 2024).
hepatoma (5 papers, 2014 to 2024). "It has been shown that LPCAT3 gene promoter contains a liver X response element (LXRE), which is regulated by LXR agonist at least in chicken and human hepatoma cells." (PMID 38694208, 2024). "Since double KDs are difficult and phenotypes are weak due to mutual compensation by the isoenzymes, we also analyzed the human hepatoma cell line HuH7, which expresses LPCAT3 and LPCAT1, but no LPCAT2." (PMID 25491198, 2014). "The upregulation of LPCAT3 mRNA expression could reflect the direct action of LXRs on the LPCAT3 promoter, which contains a functional LXR response element as observed on human hepatoma, monocytes and macrophages." (PMID 38694208, 2024).